KIF20A (kinesin family member 20A)
Diseases named in the same sentence as KIF20A in open-access papers (continued):
Sharing a sentence is not in itself a finding about the gene and the disease.
tumor (continued). "Together, our results show that KIF20A is essential for TNBC tumor growth through controlling BCSC fate." (PMID 41392981, 2025). "Mechanistic exploration reveals that KIF20A orchestrates an immunosuppressive tumor microenvironment characterized by diminished PD-L1+ tumor cell density." (PMID 41267030, 2025). "The primary focus is on the development of specific KIF20A inhibitors, detailing their roles and the challenges encountered in enhancing their efficacy, such as achieving specificity, overcoming tumor resistance, and optimizing delivery systems." (PMID 39272816, 2024). "Firstly, KIF20A RNA was found to be upregulated in tumor tissues compared to normal tissues across all datasets (all P<0.05)." (PMID 39555078, 2024). "To understand how KIF20A impacts essential gene expression to contribute to HCC tumor progression and clinical prognosis, we characterized changes to downstream mRNA levels in HCC." (PMID 39624268, 2024). "This highlights the versatility of KIF20A-targeted immunotherapy across different age groups and tumor types, underscoring its potential as a universal cancer therapy target." (PMID 39272816, 2024). "The HBV-HCC tissues (n = 212) showed a higher KIF20A mRNA level than non-tumor cases (n = 221) in GSE14520 dataset (p < 0.0001)." (PMID 39624268, 2024). "Mechanistically, KIF20A influences key cell cycle and apoptosis pathways, contributing to tumor growth and metastasis." (PMID 39555078, 2024). "UCA1 was once again shown accountable for driving aggressive tumor growth, through its interactions with proteins such as KIF20A, and by sponging different miRNAs, such as miR-299-3p, miR-145, and miR-155." (PMID 38534790, 2024). "HCC tumor has 31.35% heterozygous amplification, 10.81% heterozygous deletion and 1.08% homozygous amplification in KIF20A gene." (PMID 39624268, 2024). "KIF20A, a mitotic kinesin overexpressed in various cancers, plays a pivotal role in cell division and is increasingly recognized as a crucial factor in tumor progression and a potential target for novel cancer treatments." (PMID 39272816, 2024). "Firstly, more detailed in vivo animal experiment data, including liver-to-body weight ratio, can provide more information on the impact of KIF20A on tumor burden." (PMID 39555078, 2024). "Recent findings indicate that KIF20A suppression leads to early cell cycle exit and accelerated neuronal differentiation in both normal cerebellar granule neuron progenitors (GNPs) and tumor-initiating GNPs." (PMID 39272816, 2024). "This includes exploring adjuvants that can enhance the immunogenicity of KIF20A peptides and strategies to overcome tumor-induced immunosuppression." (PMID 39272816, 2024). "This diversity can affect the expression levels of KIF20A and, consequently, the effectiveness of KIF20A-targeted therapies across and within tumor types." (PMID 39272816, 2024). "For example, KIF3A and KIF13A are essential for cancer cell migration, a Kinesin13 family member MCAK leads to tumor invasion and paclitaxel resistance, and KIF20A and KIF15 contribute to the castration and Enzalutamide resistance of prostate cancer." (PMID 37711200, 2023). "Five GRGs (ABCB6, ANKZF1, B3GAT3, KIF20A and STC2) were dysregulated in tumor samples and were independently associated with the prognosis of HCC." (PMID 35123420, 2022). "The prognostic significance of KIF20A has also been evaluated in other solid tumors, where it has been demonstrated that it plays a vital role in cell proliferation and tumor metastasis." (PMID 36619388, 2022). "Functionally, the overexpression of KDELR2 and KIF20A markedly promoted proliferation, migration, and invasion in vitro and enhanced tumor growth in vivo, while knockdown of KDELR2 and KIF20A exerted the opposite effects." (PMID 36096734, 2022). "ESTIMATE and CIBERSORT algorithms were then used to study the association of KIF20A with the tumor microenvironment (TME) and the percentage of tumor-infiltrating immune cells (TICs)." (PMID 36619388, 2022).
tumor (continued). "Despite evidence highlighting the roles of KIF20A in various tumor cells and its importance in regulating tumorigenesis, the underlying mechanism in BCa remains largely elusive." (PMID 36096734, 2022). "Collectively, the results demonstrated that KIF20A played a critical role in the proliferation, invasion and chemotherapeutic drug sensitivity of the tumor cells." (PMID 36096734, 2022). "Although abnormal expression of KIF20A has been reported in BCa, the present study is the first to reveal its specific mechanism in promoting tumor progression and regulating the expression of MMPs." (PMID 36096734, 2022). "Overexpression of KIF20A was significantly correlated with poor oncologic outcomes and tumor progression in OC patients, which is consistent with previously reported studies." (PMID 35204562, 2022). "To study the possible mechanism of inhibition of SHH-induced MB by LOF of KIF20A, we looked at cell cycle exit and re-entry in tumor-initiating GNPs of the Ptc single- and Ptc/Kif20a double-knockout mice." (PMID 33976373, 2021). "Our results showed that tumor cells derived from the Ptc/Kif20a double-knockout mice had a slower proliferation rate, consistent with the overall longer survival time of the double-knockout mice." (PMID 33976373, 2021). "TIMER tool further revealed expression of the 5 signature genes (ZNF695, CENPA, TROAP, BIRC5 and KIF20A) was strongly and positively correlated with high tumor purity but negatively influenced the infiltration of CD8+ T cells and macrophages." (PMID 33995639, 2021). "Kinesin family member 20A (KIF20A), a member of kinesin superfamily 6, plays a significant role in the occurrence and development of tumours." (PMID 34425834, 2021). "After the overexpression of IRF6, the expression of IRF6 in tumor tissues increased, while the expression of KIF20A decreased." (PMID 33941190, 2021). "We next examined the expression status of KIF20A in relation to human MB cells using available expression data of patient tumor samples." (PMID 33976373, 2021). "Among the different analysis methods and cancer types, the kinesin family members KIF20A and KIF23 were consistently among the top genes associated with malignant transformation or tumor stage." (PMID 33819271, 2021). "To further test the effect of Kif20a deletion, we next introduced Cre enzyme (Cre-2A-GFP), or control green fluorescent protein (GFP), into the tumor cells derived from the Ptc/Kif20a double-knockout mice, using a lentiviral expression system." (PMID 33976373, 2021). "In tumors, Kif20a expression increased significantly, it promoted the growth of tumors and tumor cell lines, and was related to carcinogenesis and aggressiveness." (PMID 32742456, 2020). "Downregulation of Kif20a inhibited proliferation and colony formation in vitro and suppressed tumor growth in vivo." (PMID 32742456, 2020). "The overall disease free survival was 15.8 months for patients treated with OCV-C01 and gemcitabine, and survival was significantly correlated with Kif20A expression in tumor specimens." (PMID 33050151, 2020). "We found that Kif20a regulated cell division and contributed to tumor growth both in vitro and in vivo and in STSs." (PMID 32742456, 2020). "In vivo experiments revealed that Kif20a affected the proliferation of tumors in tumor-bearing mice." (PMID 32742456, 2020). "Histone H3-variant-centromere-protein A (CENPA), KIF20A and CDCA8 are hub genes that are overexpressed in PCa development and tumor progression." (PMID 33375045, 2020). "Our results revealed that KIF20A is correlated with high immune infiltration of ccRCC tumor microenvironment." (PMID 33232285, 2020). "In vitro experiments suggest that KIF20A is highly expressed in ccRCC tissues and possibly responsible by promoting tumor proliferation and invasion." (PMID 33232285, 2020). "Because KIF20A is closely related to cell division, a significant feature of malignant tumours is uncontrolled cell growth." (PMID 31093305, 2019).
tumor (continued). "The in vivo experiments confirmed that tumour growth was significantly inhibited after knocking down KIF20A." (PMID 31093305, 2019). "Statistical results showed that patients with a higher expression of KIF20A had a higher tumour grade and a more advanced stage." (PMID 31093305, 2019). "Western blot results showed that the expression level of the KIF20A protein was higher in the tumour tissue than in the adjacent tissues." (PMID 31093305, 2019). "The tumors formed by KIF20A-transduced CRC cells grew more rapidly and were larger in size than those of the control group, indicating that KIF20A overexpression also significantly aggravated tumor formation and progression in vivo." (PMID 31841120, 2019). "Since tumor cells dissolve Matrigel by secreting matrix metalloproteinases, we used the Western blotting assay and found that knocking down KIF20A can decrease the expression of MMP2 and MMP9 in C4-2 cells." (PMID 31565099, 2019). "Next, we examined the role of KIF20A in tumor metastasis in vivo by injecting HepG2/wild, HepG2/metR+shGFP, and HepG2/ metR+shKIF20A cells into the tail vein of BALB/c-nude mice (n = 5 per group)." (PMID 30813560, 2019). "The role of KIF20A during tumorigenesis and tumor development has been well studied in several cancers." (PMID 31565099, 2019). "The final results showed that the tumour differentiation of patients with a high KIF20A expression was worse than that of patients with a low KIF20A expression." (PMID 31093305, 2019). "Tumor volumes of si‐KIF20A group were significantly reduced compared with those of si‐control group." (PMID 30105795, 2018). "Three weeks after tumor inoculation, the mice were injected with cholesterol‐conjugated si‐KIF20A and corresponding si‐control, respectively." (PMID 30105795, 2018). "Quantitative analysis confirmed that the average mean absorbance value for KIF20A staining was significantly higher in the tumor tissues than the normal nasopharyngeal tissues." (PMID 28081138, 2017). "Using the cutoff score of ≤ 6, 45/105 (42.9%) of tumor specimens were classified as high KIF20A-expressing and 60/105 (57.1%) as low KIF20A-expressing." (PMID 28081138, 2017). "KIF20A protein expression was also examined in archived paraffin embedded tumor samples from 105 patients with pathologically confirmed NPC by immunohistochemistry (IHC)." (PMID 28081138, 2017). "Immunohistochemistry revealed KIF20A was primarily expressed in the tumor cell nuclei with occasional strong cytoplasmic staining detected." (PMID 28081138, 2017). "A significant positive correlation between KIF20A protein staining and tumor grades was observed (P < 0.05)." (PMID 27941992, 2016). "Since KIF11/Eg5 and KIF20A/Mklp2 are promising drug targets, we sought to investigate the impact of their respective inhibitors on angiogenesis, a process that is central to tumor progression." (PMID 24327603, 2013). "KIF20A-66 peptide vaccination was well tolerated in the doses we examined and tumor responses after 1 month of the treatment were evaluated." (PMID 24237633, 2013). "In addition, we evaluated the regulatory role and immunotherapy potential of KIF20A in the tumor microenvironment through various bioinformatics algorithms." (PMID 41646843, 2026). "KIF20A (Kinesin family member 20A), a kinesin superfamily protein, functions primarily during mitosis by participating in cell cycle regulation, microtubule dynamics, and cytokinesis; its overexpression enhances tumor cell proliferation." (PMID 41246267, 2025). "Notably, however, PD-L1+ tumor cell density was significantly higher in KIF20A-low tumors compared to KIF20A-high tumors (864.8/mm2 vs. 375.4/mm2; P = 0.0002)." (PMID 41267030, 2025). "Importantly, Cox regression models revealed that risk scores based on the expression of CDC20, KIF20A and PTTG1 were independent prognostic variables than indices of tumor grade or IDH‐mutant status." (PMID 40047299, 2025).
tumor (continued). "Interestingly, berberine, a traditional Chinese medicine, has been proposed to inhibit LUAD tumour models in vivo by suppressing KIF20A and CCNE2 expression." (PMID 40002279, 2025). "Our results showed that PYCR1, INMT, and KIF20A were significantly upregulated in tumor cells." (PMID 41013841, 2025). "Through integrated bioinformatics and clinical validation, we demonstrate that KIF20A overexpression suppresses PD-L1 expression in tumor cells, shapes an immunosuppressive tumor microenvironment, and independently predicts adverse outcomes in immunotherapy-treated patients." (PMID 41267030, 2025). "KIF20A knockdown significantly inhibited tumor growth and invasion and could become a valid biomarker." (PMID 40002166, 2025). "Whether KIF20A promotes tumor progression in KIRP through metabolism-related pathways, however, requires further investigation." (PMID 41013841, 2025). "We hypothesize that high PD-L1 expression may partially restore the efficacy of PD-1 inhibitors by facilitating immune checkpoint interactions between tumor cells and T cells, thereby mitigating the KIF20A-driven oncogenic effects." (PMID 41267030, 2025). "The upregulation of KIF20A could potentially enhance the evasion of ferroptosis, promoting tumor growth and progression." (PMID 40465746, 2025). "To determine whether KIF20A regulates BCSC activity to promote TNBC tumor initiation in vivo, we performed limiting dilution assays in NOD-scid IL-2Rγ–null (NSG) mice." (PMID 41392981, 2025). "Additionally, KIF20A levels were upregulated ∼8.3-fold in HBV-related HCC tissues (n = 15) in comparation with non-tumor tissues (n = 15) in GSE135631 dataset (p < 0.0001)." (PMID 39624268, 2024). "Furthermore, KIF20A contributes to tumor resistance to chemotherapy in HCC, highlighting its potential as a therapeutic target for HCC treatment." (PMID 39624268, 2024). "Furthermore, we explored the underlying mechanisms by which KIF20A regulates HCC progression, the tumor immune microenvironment (TiME), and immune responses using both bulk RNA-seq and scRNA-seq." (PMID 39555078, 2024). "To further verify the pro-tumor effect of KIF20A, we conducted GSEA analysis using bulk RNA-seq." (PMID 39555078, 2024). "Importantly, in cancer cells, FOXM1 is often overexpressed, enhancing its ability to drive the expression of genes like KIF20A that are critical for cell proliferation and tumor progression." (PMID 39272816, 2024). "Except for the impact on proliferative vitality of tumor cells induced by KIF20A, the influence on in vitro chemosensitivity was also observed that KIF20A-silencing drastically increased sensitivity of tumor cells to cisplatin and sorafenib, while the intrinsic mechanism remained to be explored." (PMID 38433242, 2024). "The detailed examination of KIF20A’s expression, structure, and multifaceted roles in tumor progression, as discussed in this review, underscores its significance not only as a marker for cancer prognosis but also as a viable target for innovative therapeutic strategies." (PMID 39272816, 2024). "Finally, multi-dimensional single-cell sequencing technology with spatial and temporal genomics can provide more reliable evidence on the impact of KIF20A on the tumor microenvironment." (PMID 39555078, 2024). "Furthermore, a deeper understanding of KIF20A’s biological functions and its interplay with the tumor microenvironment will be crucial for developing more effective and durable cancer treatments." (PMID 39272816, 2024). "Its capacity to rapidly assess KIF20A expression patterns across various cancers, combined with a user-friendly interface designed for selecting specific cancers and comparing tumor versus normal samples, establishes it as a key resource for cancer research gene expression profiling." (PMID 39272816, 2024). "IHC analysis also confirmed KIF20A upregulation in tumor tissue of the TMA cohort (P<0.05)." (PMID 39555078, 2024).
tumor (continued). "Interestingly, KIF20A is a well-known tumor antigen, and MCM3 and MCM5 are critical controllers for regulating cell cycles." (PMID 37884996, 2023). "After injected CTL induced KIF-20A-LPs, expression of KIF20A was detected in 55% of HNMT, KIF20A specific Th1 cell response was detected after short-term stimulation of PBMC in 50% of HNMT patients, indicated that KIF20A-LP can induce tumor-specific Th1 cells and CTLs at the same time." (PMID 36798768, 2023). "KIF20A not only increased in tumors, related to OS, but also took part in tumor drug resistance." (PMID 36798768, 2023). "This study provided strong evidence for the effectiveness of KIF20A as a tumor vaccine." (PMID 36798768, 2023). "For KIF20A, high expression is underlined by the large number of epitopes that have been identified to be processed and bound to MHC complexes in a wide array of different tumor cells." (PMID 36768616, 2023). "A recent study found that KIF20A was upregulated in the lactate-enriched tumor microenvironment and could regulate microtubule dynamics and cell motility and thus contribute to cancer progression and metastasis." (PMID 35123420, 2022). "Collectively, these results suggest that upregulation of KIF20A promotes tumor progression in BCa." (PMID 36096734, 2022). "The expression of IRF6 and KIF20A in tumor tissues was detected by RT-QPCR and western blot." (PMID 33941190, 2021). "Studies had shown that KIF20A might promote the proliferation, invasion and migration of tumor cells by activating the JAK2/STAT3 pathway." (PMID 33836688, 2021). "Therefore, although it is clear that our results are predominantly dependent on inhibition of MDM4, it is possible that an effect on KIF20A is also contributing to the observed anti-tumor effects." (PMID 33536467, 2021). "As tumor-initiating (stem/progenitor-like) cells share many regulatory mechanisms of cell proliferation with normal neural stem/progenitor cells, it is conceivable that KIF20A is also crucial for the control of proliferation vs. differentiation of tumor-initiating cells." (PMID 33976373, 2021). "Our data indicated that KIF20A may promote cell invasion and proliferation in ccRCC, thus serving as an independent tumor marker and a putative therapeutic target." (PMID 33232285, 2020). "To investigate the effect of Kif20a on tumor growth, we established a tumor-bearing mouse model." (PMID 32742456, 2020). "An increased expression of KIF20A has been found in the development of various tumor diseases." (PMID 33375045, 2020). "Of note, we have also identified KIF20A as an effective tumor and prognosis marker." (PMID 33232285, 2020). "As a result, a prominent increase on KIF20A mRNA levels was observed in tumor tissue." (PMID 33232285, 2020). "In order to verify whether KIF20A can affect tumor growth in vivo, C4-2 cells knocking down KIF20A were injected subcutaneously into the groin area of nude mice." (PMID 31565099, 2019). "Furthermore, recent studies have demonstrated that KIF20A is involved in tumor progression and angiogenesis." (PMID 30778371, 2019). "High expression of KIF20A promotes tumor metastasis in various types of cancers." (PMID 30813560, 2019). "Moreover, we found that KIF20A achieved its pro-tumor function by activating the JAK/signal transducer and activator of transcription 3 (STAT3) signaling pathway." (PMID 31841120, 2019). "Patients with a higher expression of KIF20A had a higher tumour grade and a more advanced stage." (PMID 31093305, 2019). "KIF20A (kinesin family protein member) is involved in tumor growth and progression." (PMID 28052097, 2017). "In addition, the mean optical density (MOD) values for KIF20A staining significantly increased as tumor stage increased from I to IV (P < 0.05)." (PMID 28081138, 2017). "Moreover, significant evidence indicates that overexpression of KIF20A promotes cell proliferation in a variety of tumor types, indicating that KIF20A is involved in the progression of cancer." (PMID 28081138, 2017).